MMP2 (matrix metallopeptidase 2)
Diseases named in the same sentence as MMP2 in open-access papers (continued):
Sharing a sentence is not in itself a finding about the gene and the disease.
aneurysm (continued). "Histopathological features of aneurysm tissues in MFS include elastic lamellae fragmentation and disorganization, accumulation of amorphous matrix components, excessive smooth muscle cell (SMC) apoptosis, and increased expression of matrix metalloproteinase (MMP)-2 and MMP-9." (PMID 29040313, 2017). "However, besides patterns of blood flow and WSS, degeneration of the extracellular matrix in the arterial wall by upregulation of MMP2 and MMP9 or infiltration of macrophages also have important synergistic effects with hemodynamic status if an aneurysm develops or ruptures." (PMID 24195732, 2013). "MMP-2 may actually provoke aneurysm formation rather than propagate their growth, a concept that could only be verified by conducting studies early in the disease process." (PMID 24028184, 2013). "On the other hand, MMP-14, TIMP-2 and their ratio in ROC curve are negligible compared to that of MMP-2, enabling us to hypothesize that the enzymes that activate MMP-2 are not the determining enzymatic factor in aneurysm development, rather that they support the central role of MMP-2 activation." (PMID 30794673, 2019). "We found only a significantly lower mRNA expression of MMP-2 in aneurysms, whereas higher expression of MMP-9 in aneurysms was not significant between the groups as well as the expression of MMP-1 and MMP-14." (PMID 26539497, 2015). "Additionally, clodronate liposomes did not lead to a decrease in the levels of MMP2 and MMP9 in the aneurysm walls." (PMID 39595942, 2024). "The local tissue's MMP-14/TIMP-2 ratio may regulate the degree of Pro-MMP-2 activation in human aTAA as a determining factor, but MMP-14 and TIMP-2 do not seem to be enzymatically essential to aneurysm development." (PMID 30794673, 2019). "The tissue's MMP-14/TIMP-2 ratio may regulate the degree of Pro-MMP-2 activation as a determining factor, while the enzymatic activities of MMP-14 and TIMP-2 do not seem to play a key role in aneurysm development." (PMID 30794673, 2019). "Interestingly, infusion of wild type macrophages resulted in reconstitution of aneurysms in MMP9-/- mice, but not MMP2-/-, highlighting MMP-9 specific release from macrophages, as expected." (PMID 31390798, 2019). "Therefore we speculated that the increase of gelatinase activity in this experimental aneurysm was mainly MMP-2, rather than MMP-9, and MMP-2 might play a more important role than MMP-9 in aneurysm formation." (PMID 25243605, 2014).
heart failure (91 papers, 2008 to 2025). Inability of the heart to pump blood at an adequate rate to meet tissue metabolic requirements. "On the other hand, there is a strong association between MMP-2 levels with NPs in patients with heart failure." (PMID 36982395, 2023). "MMP-2 is also associated with cardiac failure, and both genetic polymorphisms commonly found in the MMP-2 gene and increased plasma MMP-2 concentrations are linked to heart failure." (PMID 33923477, 2021). "sST2, MMP-2, and NT-proBNP were all independent risk factors of heart failure which can be used for risk stratification." (PMID 32354356, 2020). "The circulating biomarkers sST2, MMP-2 and NT-proBNP were all independent risk factors for patients with heart failure." (PMID 32354356, 2020). "The markers sST2, MMP-2 and NT-proBNP are all independent risk factors for patients with heart failure." (PMID 32354356, 2020). "Further logistic regression analysis showed that except MMP-9, the biomarkers sST2 (OR = 1.960), MMP-2 (OR = 0.805) and NT-proBNP (OR = 0.002) were all independent risk factors for patients with heart failure." (PMID 32354356, 2020). "In the DOCA-salt hypertensive rat model spironolactone treatment caused improvement in functional parameters of heart failure and lower plasma MMP-2 and TIMP-1 concentrations." (PMID 31141909, 2019). "In this study, heart failure was also associated with MMP-2, GM-CSF and atherosclerotic index of plasma (AIP)." (PMID 26843213, 2016). "The separation of intracellular from extracellular roles of MMP-2 has the potential to provide new directions for studying mechanisms underlying several cardiac pathologies, including heart failure." (PMID 25147815, 2014). "Accordingly, baseline levels of MMP-2, -8 and -9 were positively associated with cardiovascular death or hospitalization for heart failure by a univariate analysis, while only MMP-8 baseline levels were an independent predictor of LV remodelling and cardiovascular outcome after MI." (PMID 37160529, 2023). "Anthracycline drugs such as DOX can enhance the activity of MMP-2 in cardiomyocytes and may cause heart failure, so inhibition of MMP-2 activity can interfere with the cardiotoxicity of anticancer drugs." (PMID 33281914, 2020). "Interestingly, Mmp2 with a score of 6 encodes matrix metalloproteinase 2 (MMP2), a Zn-binding member of MMPs, that has numerous substrates in cardiomyocytes that contribute to cardiac ischemia-reperfusion injury, cardiac remodeling, and heart failure." (PMID 36818345, 2023). "Several biomarkers—including IGFBP-1, IGFBP-2, IGFBP-3, FGF-23, MMP-2, MMP-7, TIMP-2, and RAGE/AGE—were significantly elevated in patients with cardiac involvement and independently associated with either heart failure decompensation or death/transplantation." (PMID 41226753, 2025). "qRT-PCR results indicated that MI significantly increased the mRNA levels of fibrosis-related genes (Col1, Col3, Mmp2, and Mmp9) and heart failure biomarkers (Anp, Bnp, and β-Mhc) compared to the sham group (p < 0.05 for all)." (PMID 39834616, 2025). "The biomarkers MMP-2, TIMP-1, GDF-15, and OPN were particularly notable for their strong associations with adverse clinical outcomes, including heart failure events and all-cause mortality." (PMID 39334904, 2024). "Although MMP2 overexpression is related to increased heart failure, the protective roles of this enzyme against cardiac hypertrophy and against Angiotensin II-induced hypertension have also been reported." (PMID 38399400, 2024). "In terms of molecular features of heart failure, low dose of PG-901 downregulated cardiac expression of Nppa, Mmp2, and Ctgf." (PMID 38454158, 2024). "In a rat model of heart failure, pravastatin suppressed the increase in myocardial MMP-2 and MMP-9 activity." (PMID 39200884, 2024). "Spironolactone treatment has been shown to reduce MMP2 and MMP9 levels in patients at risk of heart failure." (PMID 36749631, 2023).
heart failure (continued). "Increased MMP2 activity has been observed in the myocardium of hypertensive mice with heart failure." (PMID 37512106, 2023). "H2S also provides a clinical possibility for the prevention and treatment of heart failure by upregulating MMP2, downregulating MMP‐9 and TIMP‐3, and promoting angiogenesis through the eNOS‐NO pathway." (PMID 36478328, 2023). "The abundance of MMP2 mRNA was similar in all tissues and there was a significant PAH-dependent upregulation in MMP2 mRNA in the right atrium as has been observed by others in the working myocardium in various species and heart failure models." (PMID 37122221, 2023). "TGF-β1 induced the expression of key fibrotic proteins collagen type 1 and MMP2, but also less well-known heart failure related proteins, such as OPG, IGFBP7, PAI, uPA, and U-PAR." (PMID 35360018, 2022). "The result is an activated p65 which binds to the promoter site of NF-кB in the human antigen R (HuR) eliciting a binding activation to the MMP2, leading to collagen degradation and eventual heart failure." (PMID 35668933, 2022). "TIMP-2 has the specific ability to stimulate collagen synthesis, and MMP-9 seems to be more activated in heart failure with reduced ejection fraction and dilated cardiomyopathies than MMP-2." (PMID 36005418, 2022). "An increase in hypomethylation of MMP2 has been previously reported in blood samples and cardiac tissues of heart failure patients." (PMID 35668933, 2022). "The myocardial expression of MMP-2 has been noted to increase with heart failure and pressure overload." (PMID 34867466, 2021). "In atrial biopsies, the downregulation of TIMP-2 and upregulation of MMP-2 correlates with the development of sustained AF in patients with cardiomyopathy and heart failure." (PMID 34203369, 2021). "In both experimental and clinical forms of heart failure, there is an increase in the cardiac content of MMP-2 and MMP-9." (PMID 33806909, 2021). "Previous studies conducted on rats have shown that the plasma levels of MMP-2 and TIMP-1 reflect heart failure associated with haemodynamic, functional, and morphological changes." (PMID 34930125, 2021). "It was shown that in a rat model of heart failure, pravastatin suppressed the increase in myocardial MMP-2 and MMP-9 activity." (PMID 32486345, 2020). "MMP2/TIMP4 ratio has been reported to be increased in heart failure induced by occlusion of the left coronary artery in spontaneously hypertensive rats." (PMID 33129260, 2020). "TIMP2 is highly expressed in the myocardium and has the dual actions of activating pro-MMP2 and blocking the activation of MMP2, which inhibit angiogenesis and the development of heart failure." (PMID 31182988, 2019). "Of these, IL6, MMP2, and MMP9 are established risk correlates and mediators of adverse myocardial remodeling in heart failure." (PMID 30089854, 2019). "Circulating levels of matrix metalloproteinase-2 (MMP-2) predict mortality and hospital admission in heart failure (HF) patients." (PMID 27551966, 2016). "Among the secreted MMP members, we selected collagenase MMP-1 and gelatinase MMP-2, which are up-regulated in abnormal arteries and in heart-failure patients, respectively." (PMID 26495844, 2015). "We have shown previously that during compensatory cardiac hypertrophy, MMP-2 expression was increased promoting angiogenesis while MMP-9 expression supersedes in de-compensatory heart failure promoting anti-angiogenesis." (PMID 24711742, 2014). "On the other hand, the suppression of Mmp2 activity by angiotensin-converting enzyme inhibitors can prevent left ventricular remodeling in a rat model of heart failure (L2)." (PMID 24564975, 2013). "By univariate analysis, there were positive relations between cardiovascular death or hospitalization for heart failure during the 3-year follow-up and the baseline levels of MMP-2 (P = 0.03), MMP-8 (P = 0.002), and MMP-9 (P = 0.03)." (PMID 23967183, 2013).
heart failure (continued). "Therefore, MMP-2 is involved in the modulation of inflammatory intracellular pathways and cardiac metabolism and has been quantified as a predictor of heart failure." (PMID 39408865, 2024). "Treatment with H2S donors could inhibit the transition from compensatory hypertrophy to heart failure by inducing the production of MMP‐2, inhibiting the expression of TIMP‐3 and MMP‐9, and promoting the synthesis of VEGF." (PMID 36478328, 2023). "The expression of this zinc-dependent protease is regulated by mechanical signals, inflammatory factors, hormones, and NPs, among other factors; some authors even suggest that MMP-2 can be used as a possible pharmacological target in the treatment of heart failure." (PMID 36982395, 2023). "Activation of MMPs, especially the gelatinases MMP-2 and MMP-9, is associated with adverse remodeling and LV dilatation in heart failure patients, and precedes LV dysfunction in animal models with tachycardiomyopathy, suggesting that they are early markers of cardiomyopathy." (PMID 34052857, 2021). "MMP2 activation surely results in extensive extracellular matrix remodeling which is the primary determinant of passive left ventricular properties and plays a key role in force transmission and heart failure progression." (PMID 29769710, 2018). "We found that galectin-3 and MMP-2 were significantly associated with global cardiac fibrosis, even after adjusting for confounding risk factors, whereas TIMP2 and NT-proBNP were significantly associated with the aggravation of heart failure symptoms." (PMID 30413105, 2018). "In addition, MMP2 was also actively up‐regulated as a result of the AVF heart failure model and was evaluated by in gelatin zymography." (PMID 27396717, 2016). "Increased activity of the MMP-2 into the perfusate contributes to the disruption of the endothelial layer and has a negative impact on the vascular permeability and leads to coronary artery disease and heart failure." (PMID 25874025, 2015). "In particular, an increase of TIMP-1 appears associated with the raising of circulating levels of MMP-2 and MMP-9, not only in patients at the final stage of heart failure (or in the acute state of decompensation), but also in patients with subclinical heart failure." (PMID 26495844, 2015). "MMP-2, as a critical prognosis for heart failure, was also detected in present study." (PMID 23861715, 2013). "Pathological activation of intracellular MMP-2 is an underlying cause of cardiac failure following ischemic reperfusion, but the intracellular role of Mmp2 during embryonic development has never been investigated." (PMID 22952682, 2012). "Thus, induced MMP2 overexpression may be part of the protective mechanisms of eUb against heart failure." (PMID 38399400, 2024). "Moreover, to compare the physiological relevance of MMP-2 and MMP-9 in heart failure between the animal model and humans, we analyzed the expression of MMP-2 and MMP-9 in the left ventricle tissue of donated patient samples using publicly available GEO datasets." (PMID 36834504, 2023). "Further Spearman correlation analysis suggested that the MMP-2 but not MMP-9 could be used as an independent risk factors for heart failure diagnosis, which was consistent with the results of George J’s study。." (PMID 32354356, 2020). "Another study, which explored the potential significance of MMP and TIMP levels in the blood of adult patients with heart failure, found that MMP-9, along with MMP-2 and TIMP-1, serves as a mortality predictor." (PMID 39466144, 2025). "The levels of ANP, BNP, NT-ProBNP, PICP, MMP-2, MMP-9, and TIMP-1 in rat serum reflect the severity of heart failure, and the level of cAMP in myocardial tissues can reflect the activity of the cAMP signaling pathway." (PMID 38402401, 2024). "Another potential explanation for this result is a reduced MMP-2 serum levels induced by ACEI, which have been found to reduce MMP-2 levels in an experimental model of heart failure." (PMID 37122872, 2023).
heart failure (continued). "Inclusively, the expression patterns of the most proteins (MMP-2, Col1a1, Col3a1, N-Cadherin, β-Catenin, CnA, RyR, SERCA2 and PTGS2) in human heart failure are consistent with the discoveries above in the Cre recombinase-induced cardiotoxicity model." (PMID 36834504, 2023). "MMP-2 and MMP-9 are key regulators of LV remodeling and were upregulated both in MI and heart failure." (PMID 35898278, 2022). "TNF-α, MMP-2, and MMP-9 act on inflammatory processes, are upregulated during heart failure (HF), and influence ventricular remodeling." (PMID 33441969, 2021). "For example, MMP-2 and MMP-9 levels are spatiotemporal modulated after a myocardial infarction or end stage heart failure, and play important roles resulting in tissue remodeling." (PMID 34571830, 2021). "The inhibitors of MMP‐2 and MMP‐9, TIMP‐1 and TIMP‐2 are elevated in tissue and plasma during heart failure and myocardial infarction." (PMID 31932967, 2021). "The combination of increased MMP2 and decreased TGF-β1 has previously been described as anti-fibrotic in studies looking at heart failure." (PMID 32321501, 2020). "Typhaneoside regulates IL-6 and TNF-α as well as MMP-2 and MMP-9 in rats with heart failure after myocardial infarction." (PMID 31201434, 2020). "Circulating levels of MMP-2 and TIMP-1 are also elevated in chronic HF patients, significantly correlated with HF development, and correlated with the severity of heart failure." (PMID 31141909, 2019). "Results of different clinical trials suggest that plasma MMP-2 and TIMP-1 concentrations can be useful to assess disease severity in patients suffering from hypertrophic cardiomyopathy or heart failure." (PMID 31141909, 2019). "Similarly, down‐regulation of MMP2 may be a late phase adaptation, since dysregulation of myocardial MMPs is generally regarded as an early contributory mechanism towards initiation and progression of heart failure." (PMID 28261787, 2017). "Elevated MMP2, TIMP1, collagen type I and III levels were reported in patients with hypertrophy and heart failure." (PMID 27494843, 2016). "Together with changes of cardiac function, it has been shown that TIMP-1 interacts with MMP-2 and MMP-9 in patients with heart failure." (PMID 26495844, 2015). "Among Tc+ individuals, those with cardiac insufficiency had higher levels of BNP, NTproBNP, troponin I, MMP-2, TIMP-1, and TIMP-2 than those with normal ejection fraction and left ventricular diameter." (PMID 25275382, 2014). "In addition, Laennec suppressed the expression of BNP and βMHC genes (which are related to the heart failure induced by continuous injection of Ang II) and that of collagen α1, TGF-β, and matrix metallopeptidase 2 (MMP2) genes in the heart." (PMID 41451368, 2025). "However, ACEI has also been found to reduce both MMP-2 and MMP-9 levels in another experimental model of heart failure." (PMID 37122872, 2023). "In previous studies, the expression of MMP-2 and MMP-9 increased in the left ventricular myocardium in patients with dilated cardiomyopathy, and the activation of MMP-2 and MMP-9 occurred in the myocardium of mice with heart failure, accompanied by extensive collagen deposition degeneration." (PMID 36771445, 2023). "MMP-2 also destroys other contractile proteins, particularly MLC2, troponin I (TnI), and titin in the ischemic myocardium, which can lead to disorders in myocardial contractility and heart failure." (PMID 35330470, 2022). "As an enzyme responsible for myocardial fibrosis, MMP‐2 may even be more sensitive than established markers, such as the brain natriuretic peptide (BNP) in heart failure patients with preserved ejection fraction." (PMID 31932967, 2021). "Our results showed higher expression of MMP-2, 7 and 9, the key gelatinases involved in ECM degradation in AFib patients corroborating previous findings on human samples, while elevated MMP-7 was seen in rats with mild and severe heart failure." (PMID 31822289, 2019).